Y_RNA (Y RNA )
Gene: Miscellaneous RNA gene on chromosome 18 (62,330,812 to 62,330,913, forward strand). Ensembl gene ENSG00000199867.
Homologues: Orthologues: chimpanzee Y_RNA (99% identical). Paralogues in human: Y_RNA (88% identical), RNY3 (87% identical), Y_RNA (87% identical), RNY3P1 (86% identical), Y_RNA (86% identical), Y_RNA (85% identical), Y_RNA (84% identical), RNY3P14 (83% identical), Y_RNA (83% identical), RNY3P5 (82% identical), Y_RNA (82% identical), RNY3P11 (81% identical), and 94 more.